Y_RNA (Y RNA )
Gene: Miscellaneous RNA gene on chromosome 16 (2,131,851 to 2,131,950, forward strand). Ensembl gene ENSG00000200059.
Homologues: Orthologues: chimpanzee Y_RNA (98% identical), macaque Y_RNA (93% identical), dog Y_RNA (80% identical), pig Y_RNA (80% identical). Paralogues in human: Y_RNA (98% identical), Y_RNA (84% identical), Y_RNA (82% identical), RNY3 (81% identical), Y_RNA (81% identical), RNY3P1 (80% identical), RNY3P4 (80% identical), Y_RNA (80% identical), RNY3P11 (79% identical), Y_RNA (79% identical), Y_RNA (78% identical), RNY3P14 (77% identical), and 91 more.